NLRP3 (NLR family pyrin domain containing 3)
Diseases named in the same sentence as NLRP3 in open-access papers (continued):
Sharing a sentence is not in itself a finding about the gene and the disease.
liver diseases (continued). "The objective is to evaluate the published articles related to the role of NLRP3 inflammasomes in common pediatric gastrointestinal and hepatic disorders in order to identify the future perspective regarding their possible therapeutic values." (PMID 41149694, 2025). "Elevated levels of IL18 have been observed in plasma and liver tissue of patients with cholestatic disorders, further supporting the involvement of the NLRP3 inflammasome in liver disease." (PMID 40089787, 2025). "The role of NOD-like receptor protein 3 (NLRP3) inflammasome in alcoholic and non-alcoholic steatohepatitis, hepatitis, nanoparticle-induced liver injury, and other liver diseases has recently attracted widespread attention from clinicians and researchers." (PMID 40868283, 2025). "Given this role, both ER stress and the NLRP3 inflammasome are currently being explored as vital targets to develop treatments for liver diseases." (PMID 40089787, 2025). "Mitochondrial dysfunction and excessive ROS production can lead to NF-κB translocation and NLRP3 inflammasome activation, promoting pyroptosis in various liver diseases." (PMID 39917567, 2025). "The NLRP3 inflammasome is involved in multiple gastrointestinal and hepatic diseases among the pediatric age group." (PMID 41149694, 2025). "Given the close relationship between NLRP3 inflammasome, IL-1β, and IL-18 and their pivotal roles in the progression of liver diseases through the recruitment of inflammatory cells, we assessed the expression of NLRP3 inflammasome." (PMID 39949920, 2025). "The NLRP3 inflammasome is a ubiquitously expressed inflammatory pathway, and growing evidence links it to liver diseases." (PMID 40868283, 2025). "Blocking the molecules involved in the pyroptosis pathway (such as NLRP3 and IL-1β) can affect the onset and progression of liver disease, providing potential therapeutic targets for liver disease." (PMID 39917567, 2025). "Background/Objectives: This review article highlights the role of the nucleotide-binding domain, leucine-rich repeat, pyrin domain-containing 3 protein (NLRP3) inflammasomes in various gastrointestinal and hepatic disorders in the pediatric age group." (PMID 41149694, 2025). "Mitochondrial dysfunction and excessive ROS production can result in NF-κB translocation and NLRP3 inflammasome activation, promoting pyroptosis in various liver diseases." (PMID 39917567, 2025). "Aberrant activation of the NLRP3 inflammasome plays a vital role in promoting inflammation and tissue damage, and is critically involved in defense against pathogen infections and liver inflammatory diseases." (PMID 41356228, 2025). "Studies have shown that Escherichia coli strains isolated from the intestinal tract of steatotic liver disease patients can translocate to the liver via the TLR2/NLRP3 pathway." (PMID 39796579, 2024). "Recent findings have also shown that dysregulated bile acids contribute to the fibrotic progression of steatotic liver disease through NLRP3 inflammasome activation." (PMID 39796579, 2024). "Although the knowledge regarding NLRP3 inflammasome activation in liver diseases is still very general, some studies on the role of this protein in HBV, HCV, and PSC are still controversial." (PMID 38674122, 2024). "Considering the complexity of the NLRP3 pathway and its molecular signalling nodes, it is important to assess both upstream and downstream molecular signalling in order to obtain a comprehensive understanding of NLRP3 involvement in liver disease." (PMID 38908436, 2024). "Nucleotide-binding oligomerization domain-like receptor 3 (NLRP3), the best-studied canonical inflammasome, plays a vital role in liver diseases, including ischemia/reperfusion injury, drug-induced hepatotoxicity, and fibrosis." (PMID 37568105, 2023). "NLRP3 inflammasome activation plays an important role in the development and progression of liver disease." (PMID 36834849, 2023).
liver diseases (continued). "This review aimed to provide up-to-date evidence for the therapeutic impact of polyphenols via the regulation of the NLRP3 inflammasome pathway, with a focus on pancreatitis, gastrointestinal and liver disorders." (PMID 37743919, 2023). "The role of NLRP3 inflammasome activation has been paid widespread attention in liver diseases, including ischemia/reperfusion injury, drug-induced hepatotoxicity, and fibrosis." (PMID 37568105, 2023). "The current review sheds light on how dietary polyphenols can regulate NLRP3 inflammasome activation in pancreatitis, gastrointestinal and liver diseases." (PMID 37743919, 2023). "Overall, our results further highlight the pivotal role of NLRP3 inflammasome pathway in the development of liver disease." (PMID 38026692, 2023). "The autophagy of hepatic macrophages can inhibit M1 polarization and activation of NLRP3 inflammasomes to regulate the liver diseases including NAFLD, liver injury, ischemia-reperfusion injury, hepatocellular carcinoma." (PMID 37171337, 2023). "Although other inflammasomes such as NLRP1, NLRP6 and NLRP12 regulates the progression of liver diseases, NLRP3 inflammasome is considered as the potent modulator of the pathophysiological function in ALD." (PMID 37520548, 2023). "In the regulation of the NLRP3 inflammasome by ER stress in liver disorders, sometimes, ER stress inhibits NLRP3, and sometimes, the opposite is true." (PMID 35408890, 2022). "All of these results highlight the key role of pyroptosis in liver disease after NLRP3 inflammasome activation." (PMID 35624734, 2022). "Based on the results of the present study, it can be concluded that NLRP3 plays an important role in liver disease progression during HCV infection through CASP1 activation." (PMID 36376416, 2022). "The role of free radicals on inflammation, fibrosis, and liver cancer of plant-derived antioxidants on proinflammatory signaling pathways, such as NF-kappaB/NLRP3 inflammasome, are important in liver disease." (PMID 36290765, 2022). "Quercetin suppressed liver inflammation through NF-B/TLR/NLRP3, reduced PI3K/Nrf2-mediated oxidative stress, activated mTOR in autophagy, and inhibited apoptotic markers associated with liver disease." (PMID 36290765, 2022). "Recently, several lines of evidence have highlighted the pivotal role of leucine-rich repeat and pyrin domain-containing protein 3 (NLRP3) inflammasome in liver diseases, such as viral hepatitis and sterile inflammatory liver injury." (PMID 35308293, 2022). "In this review, we summarized the role of ER stress and the NLRP3 inflammasome in liver disorders and analyzed the mechanisms, to provide references for future related research." (PMID 35408890, 2022). "The idea that liver-specific NLRP3 activation is required and essential for the progression of liver disease towards NASH and beyond is very interesting." (PMID 35323681, 2022). "Mitochondrial stress and lesions can promote cell death, liver fibrogenesis and inflammation in the development of liver diseases by NLRP3 inflammasome and IL-1β activation." (PMID 35365229, 2022). "The present study demonstrated increased serum NLRP3 levels in patients with HCV-related liver disease in parallel with up-regulation of NLRP3 and its activation marker CASP1 in the liver." (PMID 36376416, 2022). "ER stress and the NLRP3 inflammasome will become an important target for the treatment of liver disorders." (PMID 35408890, 2022). "So, there are many researches targeting pyroptosis for the treatment of liver diseases, mainly involving two strategies: direct inhibition of NLRP3 inflammasome and restraining of downstream signaling pathways of the NLRP3 inflammasome." (PMID 35673561, 2022). "The present study was conducted to investigate the association between NLRP3 and the progression of hepatitis C virus (HCV)-related liver disease." (PMID 36376416, 2022).
liver diseases (continued). "The importance of NLRP3 as a regulatory molecule in the pre-malignant stages of liver disease has been highlighted." (PMID 35804922, 2022). "In this review, we summarized the role of ER stress and NLRP3 inflammasome in liver disorders and analyzed the mechanisms, to provide references for future related research." (PMID 35408890, 2022). "Activation of NOD-like receptor protein 3 (NLRP3), which can be triggered by various endogenous “danger signals”, is a crucial step in the development of metabolism-related disorders and liver disease progression." (PMID 36058909, 2022). "The important role of NLRP3 inflammasome and pyroptosis in the inflammatory response during liver diseases implicate inflammasomes as promising drug targets to develop novel therapeutic approaches for liver diseases." (PMID 35624734, 2022). "In summary, inflammation is a major component in the progression of liver diseases, with important involvement of the NLRP3 inflammasome and pyroptosis." (PMID 35624734, 2022). "Canonical inflammasomes, especially the NLRP3 inflammasome, play key roles in hepatic inflammation, injury, and the pathogenesis of various inflammatory liver diseases." (PMID 35563377, 2022). "The role of NLRP3 in liver diseases has attracted increased attention and has been considered as a potential new therapeutic target for NAFLD." (PMID 36432531, 2022). "Many studies have shown the inhibited autophagy and activated NLRP3 inflammasome in liver diseases, such as drug induced acute liver injury or ischemic-reperfusion liver injury." (PMID 35308293, 2022). "Accumulating evidence indicates that ER stress and the NLRP3 inflammasome play an important role in liver disorders." (PMID 35408890, 2022). "Recently, growing evidence suggests that the NLRP3 inflammasome activation is an important regulator of pyroptosis, which plays various roles in the development of liver diseases." (PMID 33860064, 2021). "In summary, the Nlrp3 inflammasome was shown to be important in fibrosis progression in various models of murine liver disease." (PMID 35087852, 2021). "MCC950, a highly selective nod-like receptor family pyrin domain containing 3 (NLRP3) inhibitor, has already been reported to show strong hepatoprotective effects in many different liver diseases." (PMID 34869447, 2021). "Emerging evidence supports the central role of NLRP3 inflammasomes in the pathogenesis of many liver diseases, including alcoholic and nonalcoholic fatty liver disease as well as liver injury." (PMID 33573688, 2021). "In summary, the role of NLRP3 inflammasome has been studied in many types of liver diseases and has become an important target for drug design and development." (PMID 34180140, 2021). "Studies have also revealed that NLRP3 inflammasomes significantly affect the development of liver diseases and that inhibition of NLRP3 inflammasomes can reduce liver inflammation." (PMID 33688304, 2021). "The suppression of the NLRP3 complex is protective against damage related to liver diseases such as NAFLD, which are frequent and are aggravated by the aging process." (PMID 32977490, 2020). "Our findings are in line with those previously reported showing that other lectins, such as galectin-3, are able to trigger NLRP3 activation in the context of liver diseases and influenza infection." (PMID 31906385, 2020). "Many previous studies have demonstrated the key role of NLRP3 inflammasome in the progress of all kinds of liver disease models including LPS/D-Gal-induced acute liver injury." (PMID 33536915, 2020). "In this review, we provide a straightforward overview of NLRP3 inflammasome as well as several frequent liver diseases." (PMID 32211410, 2020). "In conclusion, we can affirm the role of the NLRP3 inflammasome complex in the progression of liver diseases." (PMID 32977490, 2020).
liver diseases (continued). "Liver diseases have become a severe health burden worldwide, and there is adequate evidence indicating that the regulation of NLRP3 inflammasome acts as a guard against hazard to liver." (PMID 32211410, 2020). "Recent experimental studies showed that SB exerts protective effect against lung injury and nonalcoholic fat liver disease by inhibitory effect on NF-κB and NLRP3 inflammasome pathways." (PMID 31010153, 2019). "Mcc950 specifically inhibits NLRP3 inflammasome activation in preclinical liver diseases, including steatohepatitis but a phase II clinical trial of Mcc950 for rheumatoid arthritis was suspended owing to hepatic toxicity." (PMID 31547621, 2019). "This review summarizes the immunomodulatory roles of the NLRP3 inflammasome and IL-33 in sterile liver inflammation and highlights potential therapeutic strategies targeting these pathways in liver disease." (PMID 30213101, 2018). "To date, the pathological role of NLRP3 inflammasome in liver diseases have been extensively studied." (PMID 30319645, 2018). "The relevance of NLRP3 in liver disease has focused on the mechanisms limiting inflammasome activation and on pharmacological targeting of NLRP3, as it is involved in ethanol-induced liver injury by driving liver inflammation and neutrophil infiltration." (PMID 28134813, 2017). "Specifically, blocking key molecules such as NLRP3 and Caspase-1 could help attenuate the pathological processes associated with conditions such as NASH and other liver disorders." (PMID 40398602, 2025). "Endogenous fructose production occurs in other tissues such as the liver, and the impact of UA‐polyol pathway interplay on liver disease and endothelial damage is well documented, and both UA and the polyol pathway are known to mediate activation of the NLRP3 inflammasome." (PMID 41387231, 2025). "NLRP3 is known to play a central role in inflammasome activation and pyroptosis during alcohol-related liver disease, nevertheless we cannot exclude contribution of additional pattern-recognition receptors in liver and/or brain of our alcohol-induced ACLF model." (PMID 38419842, 2024). "Activation of the NLRP3 inflammasome contributes to various inflammatory liver diseases." (PMID 38355725, 2024). "However, they have allowed significant progress in the understanding of the contribution of the NLRP3 inflammasome in human liver disease." (PMID 38908436, 2024). "More importantly, it sheds light on the involvement of NLRP3 in liver diseases." (PMID 39742284, 2024). "Previous studies showed that hADMSCs-Exo could reduce NLRP3 inflammasome activation in macrophages and enhance ant-inflammatory responses of natural killer T-cells in liver disease." (PMID 36698192, 2023). "Furthermore, BRISC is also essential for the optimal activation of IFNAR1 and NLRP3 inflammasome pathways in hepatic macrophages, both of which are involved in the pathogenesis of a wide variety of liver diseases." (PMID 37968261, 2023). "An important role of the NLRP3 inflammasome has been described in liver diseases." (PMID 37762434, 2023). "However, excessive inflammatory response regulated by NLRP3 inflammasome triggers liver disease progression." (PMID 37762434, 2023). "Recently, it's reported that abnormal activation of NLRP3 inflammasome may lead to the progression of liver disease in patients or mice." (PMID 37057212, 2023). "During the development of liver diseases, downregulation of certain miRNAs (miR-223, miR-7, miR-30e, miR-22, and miR-495) or hypermethylation of miR-145 leads to increased expression of all inflammasome components and subsequent NLRP3 inflammasome activation." (PMID 37520548, 2023). "It is not known whether BPF can trigger inflammatory responses via the NLRP3 inflammasome, which plays a major role in the development of liver disease." (PMID 37762434, 2023). "The effects of the NLRP3 inflammasome on certain liver diseases are presented below." (PMID 35804922, 2022).
liver diseases (continued). "Therefore, understanding the steps involved in NLRP3 inflammasome activation is crucial for the treatment of fibrosis-related liver diseases." (PMID 35138513, 2022). "The NLRP3 inflammasome signaling pathway plays a crucial role in liver diseases." (PMID 36077357, 2022). "Targeting NLRP3 could be a promising therapeutic strategy to limit liver damage, particularly in HCV-infected patients with advanced liver disease who are still at risk for long-term liver-related complications even after sustained virological response." (PMID 36376416, 2022). "NLRP3 inflammasome-induced cytokines release and pyroptosis processes are the key inflammatory targeting signals in liver disease; therefore, medicines involved in the regulation of the NLRP3 inflammasome represent the primary therapeutic approach for NAFLD management." (PMID 35350750, 2022). "It has been reported that treatment with antioxidants decreases ROS and consequently reduces NLRP3 inflammasome activation in a carbon tetrachloride-induced acute liver injury model, further supporting the relationship between ROS generation and NLRP3 activation in liver disease." (PMID 35624734, 2022). "In conclusion, NLRP3 plays an important role in liver disease progression during HCV infection via CASP1 activation and might be a promising therapeutic target." (PMID 36376416, 2022). "In this review, we have summarised recent studies addressing the role of the NLRP3 inflammasome and pyroptosis in the pathogenesis of various hepatic diseases, highlighting the potential application of Nrf2 inducers in the prevention of pyroptosis as liver protective compounds." (PMID 35624734, 2022). "The present study further supports the notion that the development of pharmacological inhibitors of the XBP1/NLRP3 pathway could present a new therapeutic strategy aimed at diminishing inflammatory liver diseases." (PMID 35842731, 2022). "NLRP3 activation can be triggered by various endogenous “danger signals”, and the ceramide is one of the most important “danger signals” to mediate the development of metabolism-related disorders and liver disease progression." (PMID 36058909, 2022). "The NLRP3 inflammasome-mediated cellular communication among different liver cell types in acute and chronic liver diseases from diverse liver injuries was also well-defined, indicating the pivotal role of NLRP3 inflammasome in the development of liver diseases." (PMID 35707547, 2022). "Therefore, abnormal NLRP3 inflammasome can be involved in a variety of diseases, including liver diseases." (PMID 35408890, 2022). "However, a few literatures have pointed out the specific mechanism of NLRP3 inflammasome influencing the pathogenesis of liver diseases, more studies should be conducted to explore the definite underlying mechanism." (PMID 32211410, 2020). "Fortunately, the discovery and exploration of NLRP3 inflammasome has provided a novel insight into the liver diseases, which may be further exploited as an important target for the prevention and treatment of liver diseases." (PMID 32211410, 2020). "Therefore, targeting the NLRP3 inflammasome has been explored as an effective strategy for the treatment of all kinds of liver diseases." (PMID 33536915, 2020). "And further studies focused on NLRP3 inflammasome activity may provide novel strategies for the treatments of these liver diseases." (PMID 32211410, 2020). "Increasing evidence indicates that the inflammasome is involved in various liver diseases, including liver injury, hepatitis, liver fibrosis, and cirrhosis; however, whether the NLRP3 inflammasome participates in HBx-induced hepatitis remains unclear." (PMID 32347316, 2020). "We then discuss the contribution and regulation of NLRP3 inflammasome during the pathogenesis of liver diseases, which may provide an important indication for the prevention and treatment of various liver diseases." (PMID 32211410, 2020).